RNU4-31P (RNA, U4 small nuclear 31, pseudogene)
Gene: Small nuclear RNA gene on chromosome 7 (156,872,078 to 156,872,218, forward strand). Ensembl gene ENSG00000206938.
Homologues: Orthologues: dog U4 (48% identical). Paralogues in human: RNU4-68P (85% identical), RNU4-13P (84% identical), RNU4-7P (84% identical), RNU4-44P (82% identical), RNU4-67P (82% identical), RNU4-80P (82% identical), RNU4-42P (79% identical), RNU4-58P (79% identical), RNU4-76P (79% identical), RNU4-92P (79% identical), RNU4-23P (77% identical), RNU4-56P (77% identical), and 81 more.